CXCL12 (C-X-C motif chemokine ligand 12)
Diseases named in the same sentence as CXCL12 in open-access papers (continued):
Sharing a sentence is not in itself a finding about the gene and the disease.
tumor (continued). "In addition, the high level of CXCL12 secreted by tumor-associated stromal cells upon hypoxia is critical for tumor angiogenesis." (PMID 26993780, 2016). "CXCL12 may regulate the accumulation/recruitment of immune cells through the CXCR7 receptor, which recent studies have linked to the pro-tumor effects of CXCL12." (PMID 27590504, 2016). "Further studies will be required to verify whether CXCL12 overexpression may cause PAs development or only provide a selective proliferation advantage favoring clonal expansion of cells in which tumor-promoting mechanisms are already activated." (PMID 26441831, 2015). "In addition, stem cell factor (SCF), the main growth factor of MCs, was mainly expressed around the tumor-associated vessels, and it was proposed that the tumor-derived CXCL12/CXCR4 attracted MCs." (PMID 26377554, 2015). "Furthermore, CXCL12 is also indirectly implicated in tumor pathogenesis, acting as chemoattractant for CXCR4-positive cells, directing tumor cell migration and controlling invasive and metastatic properties of CXCR4-expressing cancer cells to distant organs." (PMID 25484899, 2014). "Hypoxia enhances CXCL12 secretion in cancer-associated fibroblasts which in turn feeds tumor development either by direct stimulation of tumor cells expressing CXCR4 (paracrine effect) or recruiting endothelial cells for angiogenesis (endocrine effect; Burger and Kipps, 2006)." (PMID 24904289, 2014). "An interplay exists between CSCs, differentiated GBM cells, and the microenvironment, mainly through secreted chemokines (e.g., CXCL12) causing recruitment of fibroblasts, endothelial, mesenchymal and inflammatory cells to the tumor, via specific receptors such as CXCR4." (PMID 24904289, 2014). "In addition, hypoxia stimulates production of VEGF and CXCL12 by both tumor and normal cells, these factors are associated with M2 polarization." (PMID 25072019, 2014). "Akt1-associated CXCL12/CXCR4 signaling promotes tumor growth, suggesting that Akt inhibitors may potentially be employed as anticancer agents to target expansion of PC bone metastases." (PMID 23902739, 2013). "As CXCL12 is implicated in tumor pathogenesis, its future in immunotherapy is still being debated." (PMID 24967094, 2013). "Cxcl12 has been shown to be essential for the guidance of neuronal and glial stem cells in embryonic development, and has also been linked to angiogenesis in both embryo and tumor formation." (PMID 23717492, 2013). "The finding that tumor-associated endothelial cells express high levels of CXCL12 supported the hypothesis that this characteristic feature of GBM would involve CXCR4." (PMID 22427929, 2012). "M2-polarized tumor-associated macrophages may promote tumor cell proliferation under CXCL12 stimulation." (PMID 22529914, 2012). "Increased CXCL12 secretion also gives rise to increased microvessel density, which may also be mediated by tumor-associated macrophages, and contributes to altered tumor architecture." (PMID 22314082, 2012). "Also noted was a significant association between DFS and the expression pattern of CXCL12, specifically expression at the tumor periphery (P = 0.002)." (PMID 22295222, 2011). "CXCL12 immunopositivity was negatively associated with distant metastases and tumour grade." (PMID 20386750, 2010). "Indeed, CXCL12-vCXCR4 positive tumours were associated with higher local tumour extent (p = 0.0014) and higher UICC stages (p = 0.017)." (PMID 20386750, 2010). "Interestingly, we found that the association between tumor expression of CXCL12 and OS was stronger in studies with a high CXCL12 expression defined as above the median density value as compared to that as any positive expression of CXCL12 (HR: 2.63 vs. 1.61, p for subgroup difference = 0.03)." (PMID 40481962, 2025).
tumor (continued). "Chemokines such as CCL2, CCL18, and CXCL12 are instrumental in promoting either a pro-inflammatory M1 phenotype, which is associated with pathogen clearance and tissue damage, or an anti-inflammatory M2 phenotype, which is involved in tissue repair, fibrosis, and tumor progression." (PMID 40330466, 2025). "Clinically, elevated pretreatment CXCL12 levels (≥1.5 ng/mL) and post-treatment increases in CXCL12 are associated with reduced responsiveness to radiotherapy, suggesting that CXCL12 may mediate tumor evasion from cytotoxic therapies." (PMID 40134607, 2025). "In addition to tumor cells, cancer-associated fibroblasts (CAFs) can synthesize and secrete CXCL12." (PMID 35565443, 2022). "Additional investigation into CXCL12 induction and its downstream effects will help determine whether or not chemokine production depends causally on the protease activity, or if it is a parallel altered function of the dysregulated tumor vasculature." (PMID 36192379, 2022). "Studies have demonstrated that the immune infiltration of B cells in the tumor microenvironment is associated with a survival advantage in patients with cervical, breast, and high-grade serous ovarian cancer; B cells are recruited through the binding of CXCL12 and CXCR4." (PMID 36188003, 2022). "Upregulated expression of growth factors such as IGF1, FGF7, proteases such as MMP2, ECM constituents such as SPP1 also known as osteopontin and chemokine such as CXCL12 may indicate the presence of cancer-associated fibroblasts (CAFs) within the tumor microenvironment." (PMID 34946170, 2021). "Although chemokines derived from infiltrated dendritic cells were not confirmed to be involved in cancer pain in the current research, other cells such as macrophages in tumor microenvironment might generate massive CXCL12 to sensitize pain associated with cancers via interacting with CXCR4 in DRG." (PMID 32434423, 2020). "Furthermore, CXCL12 encodes chemokine CXCL12, which has a strong chemotactic effect on lymphocytes and plays an important role in cells, including immune monitoring, inflammatory response, tissue homeostasis, tumor growth, and metastasis." (PMID 32612856, 2020). "Furthermore, expression of the CXCR4 ligand, CXCL12, by tumor-associated fibroblasts has been shown to promote immune evasion in a murine model of pancreatic cancer, while targeting CXCR4 with specific antagonist AMD3100 facilitated immunotherapy response in these model." (PMID 30873179, 2019). "In this study, we demonstrated that the CXCR4/CXCL12 pathway was upregulated in the primary tumor and in the matched macrometastatic SLNs of luminal B BC patients who had tumor recurrence, and it was associated with characteristics of tumor aggressiveness and invasiveness such as LN involvement." (PMID 29849822, 2018). "Dimerization of CXCL12 as the ligand of CXCR4 is important as it stimulates intracellular calcium flux but fails to activate F-actin polymerization or β-arrestin 2 recruitment which has been shown to cause cellular idling that blocks the metastatic tumour formation." (PMID 28775330, 2017). "Notably, we proved that CXCR4-linked tumor burden occurred in a zebrafish Cxcl12-dependent manner." (PMID 26744352, 2016). "As we had also shown that CXCL12 was abundant in low-grade gliomas in tumor-associated endothelial cells, microglia, and entrapped neurons, we hypothesized that low levels of cAMP would promote tumor formation." (PMID 26283963, 2015). "Additionally, CXCR4 expression in tumor cells was associated with metastasis of many human malignancies favoring their migration and homing toward CXCL12 expressing organs (lung, liver, brain, lymph nodes, bone marrow; Teicher and Fricker, 2010)." (PMID 24904289, 2014). "Indeed, reduction or the loss of the local secretion of CXCL12 at the tumor site can induce the emergence of metastatic cells that may spread in the organism toward endocrine sources of CXCL12." (PMID 24906407, 2014).
tumor (continued). "Furthermore, CXCL12 expression is negatively associated with distant metastases and tumour grade." (PMID 20386750, 2010). "While our data and other studies have suggested the important role of CXCL12/CXCR4 biological axis in organ-specific tumor metastasis, studies have also suggested that CXCL12/CXCR4 may be implicated in promoting angiogenesis, tumor cell proliferation and survival." (PMID 17083723, 2006). "It directs breast and prostate cancer cells to CXCL12-rich tissues, including the lung, liver, and bone marrow, where elevated chemokine concentrations establish conducive environments for incoming tumor cells." (PMID 41596524, 2026). "The chemokine receptor CXCR4 and its ligand CXCL12 (SDF-1) constitute a critical axis in tumor biology, influencing tumor cell proliferation, invasion, angiogenesis, and immune evasion." (PMID 41750259, 2026). "Activated pancreatic stellate cells (PSCs) within the tumor microenvironment secrete CXCL12, the ligand for CXCR4, thereby promoting stemness, epithelial-to-mesenchymal transition (EMT), and chemoresistance in miCSCs." (PMID 41991735, 2026). "Blocking key signaling pathways (e.g., TGF-β, IL-6, CXCL12) can disrupt the tumor-supporting effects of CAFs." (PMID 41590379, 2026). "Activation of the C-X-C motif chemokine receptor 4 (CXCR4) by its ligand, C-X-C motif chemokine ligand 12 (CXCL12), drives tumor growth and metastasis." (PMID 41510167, 2026). "Our findings reveal that tumor-stroma crosstalk via the CXCL12/CXCR4/BMI1 axis plays a central role in sustaining miCSC-driven metastasis and therapy resistance in PDAC." (PMID 41991735, 2026). "In the stage when tumor cells enter the bloodstream, TAMs secrete CXCL12 that facilitate tumor cell adhesion to the vascular endothelium, thereby evading clearance by the immune system." (PMID 41362730, 2026). "The CXCL12/CXCR4 axis is crucial in tumor progression, especially due to its role in tumor angiogenesis, cancer cell metastasis and survival." (PMID 40211853, 2026). "The CXCL12/CXCR4 axis also orchestrates interactions with the tumor microenvironment, facilitating chemotaxis toward CXCL12-rich niches (e.g., bone marrow and brain) and modulating anti-tumor immunity via regulatory cells." (PMID 41750259, 2026). "During MF progression, CXCR4 and CXCL12 expressions increase concomitantly as the disease advances from the plaque to the tumor stage, reinforcing the crucial involvement of this signaling axes in CTCL development and progression." (PMID 41614909, 2026). "This technique has the potential to enable the precise mapping of gene expression and chemokine gradients such as CXCL12 in the vicinity of tumor cells and the surrounding stromal components in zebrafish models." (PMID 39940643, 2025). "CXCR4 antagonists (e.g., plerixafor) modulate tumour microenvironment (TME) dynamics by disrupting the CXCR4/CXCL12 chemotactic axis, thereby impeding metastatic niche colonisation through interference with tumour cell tropism." (PMID 40411322, 2025). "Another innovative approach involves CXCL12-encapsulated PLGA/pluronic NPs designed to disrupt the CXCL12/CXCR4 signaling axis—a key driver of tumor cell migration and metastasis." (PMID 41376820, 2025). "This molecule is the ligand of the chemokine CXCL12, directly involved in the recruitment and renewal of CSCs, but also in the remodeling of the tumor microenvironment." (PMID 40573308, 2025). "In previous reports, we showed the role of GLI transcription factors (mainly GLI1) in CAFs to regulate the secretion of CXCL12 to promote tumor cell migration." (PMID 40449600, 2025). "Specifically, excluding the only study with prospective design and RT-PCR for evaluating tumor CXCL12 expression showed consistent result (HR: 1.85, 95% CI 1.49–2.29, p < 0.001; I2 = 24%)." (PMID 40481962, 2025). "CXCL12, a chemokine involved in tumor progression and metastasis, has been inconsistently associated with GC survival." (PMID 40481962, 2025).
tumor (continued). "In vivo, studies demonstrated that HMGA2-mediated regulation of macrophage polarization through the CXCL12/CXCR4 axis significantly promotes tumor metastasis." (PMID 40351420, 2025). "Previous research has shown that Tc17 cells can induce tumor cells to secrete CXCL12, thereby recruiting MDSCs that, in turn, exert an immunosuppressive effect on the cytotoxic activity of CD8+ T cells." (PMID 40452847, 2025). "CXCR4 antagonists disrupt the CXCR4/CXCL12 signaling pathway, thereby enhancing the efficacy of chemotherapy by increasing drug delivery to the tumor and reducing resistance mechanisms driven by hypoxia and stromal interactions." (PMID 40075611, 2025). "Neutrophils attracted by CXCL12 can enhance tumor progression by promoting angiogenesis, ECM remodeling, and immune suppression in the TME." (PMID 40486614, 2025). "On the one hand, they secrete the chemokines CCL3 and CXCL12, which recruit macrophages to the tumour site." (PMID 39827226, 2025). "For example, this pro-tumor effect of CAFs can be mediated in GC by CXCL12 and its receptor CXCR4 released by CAF in an autocrine and paracrine manner, respectively." (PMID 40485724, 2025). "In the mouse tumor model, the NQO1‐overexpressing group exhibited faster tumor growth and larger tumor volumes, with significantly elevated levels of CXCL12 in peripheral blood." (PMID 41028931, 2025). "TAM, on the other hand, promotes the activation of CAF and enhances the aggressiveness of tumor cells by producing molecules such as IL-6, CXCL12, and TGF-β." (PMID 40370720, 2025). "CAFs promote tumor growth and metastasis by secreting immune-suppressive factors (e.g., IL-6, TGF-β, CXCL12) and by altering the physical properties of the tumor stroma." (PMID 40038745, 2025). "FAP+ stromal cells have been shown to suppress anti-tumor immunity, and CXCL12 produced by FAP+ CAFs drives T cell exclusion and blunts responses to αCTLA-4/αPD-L1, findings that motivated later CXCR4-blockade combinations." (PMID 40940809, 2025). "Among the essential genes identified in CAFs, ALDOA and CXCL12 stood out due to their potential implications in promoting tumor growth and metastasis." (PMID 41584584, 2025). "The CXCR4/CXCL12 axis certainly facilitates tumour cell homing, specifically in organs such as the lung, liver, bone, and lymph nodes, which are the most common sites of TNBC metastasis." (PMID 41002447, 2025). "Cisplatin treatment has been shown to reduce tumour size while also increasing secretion of CXCL12, recruitment of metastasis initiating cells and pro-invasive CXCR4+ macrophages, that promote spontaneous metastasis." (PMID 39982274, 2025). "These mediators exert dual immunosuppressive effects: CXCL12 not only induces spatial exclusion of T cells from tumor cores but also disrupts dendritic cell maturation, while TGF-β drives the differentiation of naïve T cells into regulatory T cells (Tregs)." (PMID 40534854, 2025). "The debris from the TNBC cells provides antigen presentation and promotes enhanced anti-tumour immunity within the microenvironment by resolving the CXCR4/CXCL12-mediated immunosuppressive microenvironment and promoting tumour-specific immunity." (PMID 41002447, 2025). "In PDAC, CXCL12 secreted by CAFs contributes to tumor progression and gemcitabine resistance by enhancing SATB expression." (PMID 40136652, 2025). "In tumor contexts, malignant cells co-opt this pathway to metastasize to CXCL12-rich organs via Gαi-dependent upregulation of integrin α4β1 and cytoskeletal reorganization." (PMID 40552145, 2025). "This is achieved through downregulation of tumor-derived CXCL12 via the NF-κB/ERK1/2 signaling pathway, which delays macrophage polarization towards the M2 phenotype." (PMID 40490812, 2025). "Future studies should increase the sample size and focus on specific tumor types to better elucidate the prognostic significance of stromal CXCL12 expression in canine cancers." (PMID 40849508, 2025).
tumor (continued). "CXCL12 can recruit immune cells and other cell types, promoting their localization within tumor tissues." (PMID 41584584, 2025). "The CXCL12/CXCR4 axis is crucial for fostering an immunosuppressive microenvironment that supports tumor growth and metastasis." (PMID 41245887, 2025). "Pharmacological blockade of TGF‐β1 and CXCL12 effectively mitigated the tumor‐promoting effects of CMTM4 overexpression in vivo." (PMID 40433989, 2025). "CXCL-12 in tumor and IL-32 in ascites were positively correlated with increased surgery duration, indicating their role in systemic inflammation." (PMID 40652770, 2025). "In the tumor microenvironment, CXCL12 secreted by stromal cells like CAFs/PSCs and potentially nerves attracts CXCR4-overexpressing PDAC cells, guiding their migration toward neural structures and facilitating PNI." (PMID 40909268, 2025). "These cells, in turn, secrete VEGF, EGF, HGF, PDGF, CXCL12, and IL-8 to sustain tumor growth, angiogenesis, and immune infiltration." (PMID 40963620, 2025). "For instance, research has shown that CAF-derived CXCL12 enhances immune escape mechanisms in BC by regulating PD-L1 expression and promoting tumor cell proliferation, invasion, and migration." (PMID 40177538, 2025). "Targeting DNMT1 in immunocompetent mouse models significantly elevated CXCL12 expression in tumours, resulting in a robust immune response and the eradication of early lung metastases." (PMID 40442778, 2025). "Our study revealed that tumor-derived exosomes under hypoxic condition carrying HIF2A facilitated pre-invasive intestinal niche formation by inducing fibroblasts to secrete CXCL12, which supports M2 macrophage enrichment in peritumor tissues." (PMID 40756343, 2025). "CXCL12, abundantly secreted by CAFs, creates chemokine gradients that physically segregate effector T cells from the tumor core, thereby impairing anti-tumor immune responses." (PMID 41179287, 2025). "The results found that CXCL12 expression in the peritumor intestine was significantly higher than in the normal intestine and tumor tissues." (PMID 40756343, 2025). "C-X-C Motif Chemokine Ligand 12 (CXCL12) secreted by CAFs binds to tumor cell CXCR4, thereby activating downstream signaling that enhances cancer stem cell (CSC) drying and invasion, leading to tumor progression and metastasis." (PMID 41346633, 2025). "The CXCR4/CXCL12 axis occupies the intersection of intrinsic tumour cell survival, stemness, metastatic dissemination, and immune suppression." (PMID 41002447, 2025). "miR-342 targets CXC motif chemokine 12 (CXCL12), disrupting the CXCL12/CXC chemokine receptor type 4 (CXCR4) loop that sustains β-catenin activity in the tumor microenvironment, thus suppressing proliferation and enhancing apoptosis." (PMID 40943288, 2025). "Overexpression of the chemokine receptor CXCR4 has been found to promote tumor growth, metastasis, and invasion through a variety of mechanisms, including regulation of tumor angiogenesis, immune escape, and the CXCL12/CXCR4 signaling pathway." (PMID 41473685, 2025). "CAFs also produce stromal-derived factor-1 (SDF-1/CXCL12), which has been implicated in tumor cell survival and evasion of anti-angiogenic treatments." (PMID 40534854, 2025). "The results showed a pattern in which PECAM1, VWF, CXCR4, and CXCL12 appeared to infiltrate regions of the tumor delineated by HE staining and EPCAM." (PMID 39965034, 2025). "Factors associated with angiogenesis and metastasis, including VEGF and CXCL12, were selected for their contributions to tumor vascularization and dissemination." (PMID 40652770, 2025). "CXCL12 is secreted by tumour cells across multiple cancer types, including advanced cervical cancer, malignant pleural mesothelioma, ovarian cancer, and renal cell carcinoma, facilitating the recruitment of TAMs and Tregs." (PMID 40361472, 2025). "In contrast, iCAFs, which reside farther from tumor nests, secrete large quantities of pro-inflammatory mediators, including IL-6, CXCL12, and LIF." (PMID 41341574, 2025).